CXCR6 (C-X-C motif chemokine receptor 6)
Diseases named in the same sentence as CXCR6 in open-access papers (continued):
Sharing a sentence is not in itself a finding about the gene and the disease.
tumor (continued). "Blocking CXCR6 expression with shRNA has demonstrated reduced tumor growth, cytokine secretion, invasiveness, and metastasis in xenograft studies, validating CXCR6, as a therapeutic target in HCC." (PMID 41375019, 2025). "ITGA5+ PanCK+ tumor cells, corresponding to the Carcinoma 3 cluster, were localized at the tumor–stroma boundary, and CXCR6+ FOXP3+ CD3D+ regulatory T cells were observed in close proximity within the adjacent stroma." (PMID 40776410, 2025). "Pan-cancer analyses using large-scale single-cell data highlighted a close relationship between CXCR6 expression and T-cell exhaustion, suggesting a critical role for CXCR6 in tumor-immune evasion." (PMID 40394037, 2025). "The chemokine receptors CCR6, CCR7, CXCR3, CXCR4, CXCR5, and CXCR6 have the highest expression across lymphocytes, and CCR8, a known hallmark of tumour infiltrating Treg cells, is exclusively expressed on Treg cells." (PMID 39915477, 2025). "CXCR6 is another chemokine receptor that plays a crucial role in the tumor microenvironment, particularly in the context of T-cell migration and immunotherapy efficacy." (PMID 41149503, 2025). "Radiotherapy ignites the cytosolic DNA–cGAS–STING–type I IFN circuit in SCLC, thereby transforming an immunologically “cold” tumor into an inflamed microenvironment rich in neoantigens and CXCR6+ CD8+ T cells." (PMID 41415276, 2025). "CXCR6-deficient T-cells or those treated with CXCL16-blocking Abs show impaired retention and reduced local anti-tumour activity." (PMID 40361472, 2025). "Advanced HCC stages demonstrated altered NK cell phenotypes, with reduced cytotoxic activation (CD16) and increased residency markers (CXCR6/CD69) in tumor-isolated lymphocytes." (PMID 40547009, 2025). "Western blotting and ELISA confirmed that the protein levels of Cxcr6 and Ccl5 were also significantly elevated in tumours from the PR + IRT and FRA + IRT groups." (PMID 40715695, 2025). "Recent studies have highlighted the activation of the CXCL16/CXCR6 axis as a pivotal element in T cell-mediated tumor immunity, which is consistent with the increased proportion of CXCR6-high T cells we detected in interactions with M1-like TAMs." (PMID 41031375, 2025). "The roles of the other receptors are more complex; for instance, CXCR6-deficient cells accumulate in lymphoid tissues after P1C4 treatment, suggesting impaired migration to the tumor or inability to establish tissue residency status." (PMID 41415437, 2025). "The results indicated that Tc17 cells adjacent to CXCL16+ tumor cells exhibited higher CXCR6 expression." (PMID 40452847, 2025). "Specifically, CR scores (based on CXCR6, CXCR3 and CCR5 expression) were not only associated with significant differences between these tumor types but also linked to improved overall survival uniquely within brisk tumors." (PMID 41415437, 2025). "In preclinical models of NASH-related hepatocellular carcinoma, anti-PD1 treatment leads to more and larger tumor nodules, which are linked to an increase in CD8+PD1+CXCR6+TOX+TNF+ T cells." (PMID 40236693, 2025). "Tumor NKdim cells of the aHCCbp group had higher expression of the activation marker NKG2D and of the markers CXCR6/CD69 than aHCC, associated with liver residency but in contrast had reduced expression of the activation marker CD16." (PMID 40547009, 2025). "Induced CXCR6+ CD8+ T cells display tumor antigen specificity and are capable of augmenting the efficacy of anti-PD-1 therapy, resulting in slowed tumor progression." (PMID 41149503, 2025). "Critically, they also establish that the enrichment of CXCR6-co-expressing T-cell subsets within the tumor itself is a key feature of a successful anti-tumor response to immunotherapy." (PMID 41415437, 2025). "CXCR6, a receptor for the ligand CXCL16, is linked to cancer progression, promoting tumor growth and leukocyte migration." (PMID 40236693, 2025).
tumor (continued). "Taken together, these results suggest that T-cell maturation within the tumor involves programmed, sequential co-expression of CXCR3, CCR5 and CXCR6 followed by a gradual loss of these receptors in the terminally differentiated phase." (PMID 41415437, 2025). "Real-time qPCR analysis of tumour tissues revealed that propionate treatment significantly upregulated the transcriptional levels of Meox1, Cxcr6, and Ccl5, whereas Meox1-siRNA administration abolished these effects." (PMID 40715695, 2025). "Another strategy implies the engineering of therapeutic cells, such as CAR-T cells, to be “armed” with chemokine receptors, such as CXCR6, which more effectively drive their infiltration to the tumor site." (PMID 39596815, 2024). "The model incorporated age at surgery, tumor stage, and CXCR6 expression as key predictors, with higher total scores indicating worse prognosis." (PMID 39588301, 2024). "After adjusting for confounding factors such as age, gender, tumor weight, stage, and necrosis, multivariate analysis showed that CXCR6 expression was an independent prognostic factor for both OS and RFS." (PMID 39588301, 2024). "The same study also showed that CXCR6 promotes the migration and interaction of tumor-reactive T cells with intratumoral dendritic cells and subsequent antitumor activity." (PMID 38335302, 2024). "CXCR6 expression correlates with enhanced immune surveillance and anti-tumor responses, particularly through its role in the CXCL16-CXCR6 axis." (PMID 39588301, 2024). "While these findings broaden our understanding of CXCR6’s role in the tumor microenvironment, further studies are required to validate its clinical utility and to elucidate its detailed mechanisms in MIBC progression." (PMID 39588301, 2024). "Multiple immune-associated genes such as CD79A, CD3E, CD3D, ZAP70, CXCR6, and GZMA were upregulated in hot tumor regions." (PMID 38803565, 2024). "The responders’ peripheral and tumor-infiltrating CD8+MAIT cells showed an upregulated CXCR6 expression." (PMID 38698468, 2024). "Increasing evidence suggests that the CXC chemokine receptor 6 (CXCR6) is involved in tumor progression and the regulation of tumor immunity." (PMID 39588301, 2024). "The expression of CXCL16 by tumor cells traps CXCR6+ effector T cells in the tumor mass, limiting the generation of memory T cells by sequestering their precursors in the tumor." (PMID 38509063, 2024). "Considering the spatial positioning of CXCL16-expressing cells and their impact on the CXCR6+ T cells within the tumor microenvironment is crucial." (PMID 38509063, 2024). "In light of this, we investigated how CXCR6 shaped the immunogenic features of the tumor microenvironment in MIBC." (PMID 39588301, 2024). "In the context of CAR-T cells, where trafficking is a major challenge, overexpressing CXCR6 in CAR-T cells improves their trafficking when CXCL16 is highly expressed on tumor cells." (PMID 38509063, 2024). "Elimination of CXCR6 in these specific CD8+ T cells leads to reduced retention within tumor tissues, resulting in a weakened resident memory response and compromised control over OC." (PMID 38903506, 2024). "Tumor-derived CXCL16 interacts with MSC CXCR6 to modify MSCs into CAFs, which release significant amounts of CXCL12." (PMID 38745115, 2024). "Given the earlier findings that CXCR6 promoted anti-tumor immunity in MIBC, we investigated its potential role in predicting immunotherapy response." (PMID 39588301, 2024). "Functional studies in vitro and in vivo identify a specific subset of CAFs termed glycolytic cancer-associated fibroblasts (glyCAF), which rely on glycolysis to impede cytotoxic T-cell entry into the tumor mass via the Cxcl16/Cxcr6 axis." (PMID 38509063, 2024). "Initially identified as a co-receptor for HIV on human memory T cells and NK cells, CXCR6 has more recently been recognized for its involvement in tumor immunity." (PMID 39588301, 2024).
tumor (continued). "Previous have demonstrated that tissue resident CXCR6+ CD8 T cells are important components of tumor-infiltrating lymphocytes, which further evolve into GZMK+HAVCR2- subsets and terminally differentiated T cells." (PMID 37593098, 2023). "In particular, CXCR6+ CD8 cells were characterized as tissue resident and tumor reactive T cell populations, and were associated with high infiltration and responsiveness to ICB." (PMID 37593098, 2023). "CXCR6 have been reported to play an key role in sustained tumor control mediated by CD8+ cytotoxic T cells (CTLs)." (PMID 37593098, 2023). "As seen in PCa, primary breast cancer tumors recruit CXCR6 expressing MSCs via CXCL16, and the tumor-associated MSCs then secrete other chemokines, such as CCL5 and CXCL10, that promote invasion and metastasis." (PMID 37025604, 2023). "One key insight from our research is the pivotal role of CXCR6 in T-cell activation and initial migration into tumor tissues." (PMID 38299146, 2023). "To investigate the underlying mechanism of migration, we isolated T cells from donor mice two weeks after tumor injection, with control T cells labeled 45.1 and CXCR6 knockout T cells labeled CD45.2." (PMID 38299146, 2023). "We found that the proportion of CD8+ T cells expressing proinflammatory/pro‐tumour cytokines/molecules was higher than that of other immune cells, especially Ltb, Pdcd1, Cxcr6 and Il1b." (PMID 37997519, 2023). "For example, suppression of CXCL16 receptor CXCR6 was found to reduce tumor angiogenesis in a hepatocellular carcinoma xenograft mouse model." (PMID 37272931, 2023). "Conversely, our findings highlight the essential role of CXCR6 expression in facilitating T-cell activation and initial migration to tumor tissues." (PMID 38299146, 2023). "We observed a significant increase in the frequency of the effector like CXCR6+CD44+ cluster in the tumor from Arid2-deleted CD8+ T cell recipients compared with the control (26.2% versus 8.72%)." (PMID 37330910, 2023). "Single cell analysis revealed that LTA was expressed primarily in tumor infiltrating T lymphocytes and partial B lymphocytes, whereas CXCR6 was enriched predominantly in T and NK cells." (PMID 37593098, 2023). "Previous reports have demonstrated that CXCR6 plays an important role in CXCR6+ NK cell recruitment to tumor tissue and participate in anti-tumor immunity." (PMID 37593098, 2023). "In a mouse melanoma model, CXCR6 expression has been shown to result in the presence of tumor-specific CD8+ TRM cells within CXCL16+ DC clusters in the skin, ensuring the persistence and functioning of these cells." (PMID 37545498, 2023). "Meanwhile, CXCL16 expression promotes the accumulation of tumor-specific CXCR6+CD8+ T cells in tumor tissues." (PMID 36966334, 2023). "Both CXCR3 and CXCR6 were expressed at highest frequencies on tumor center trNK cells and CD8+ TRM cells, respectively." (PMID 37448786, 2023). "Cxcr6 is a classical biomarker of resident memory CD8+ T (Trm) cells to sustain tumor control 41, 42, and our results demonstrated that Klf5 deletion specifically promoted the infiltration of Cd8+Cxcr6+ T cells in tumors." (PMID 36923542, 2023). "Patents are pending for CXCR6 transduced T cells for targeted tumor therapy, Improving adoptive cellular therapy, CCR8 transduced T cells for targeted tumor therapy and CSF1R-targeted immunotherapies." (PMID 37534876, 2023). "Specifically, our findings suggest that CXCR6 expression is crucial for T-cell activation and migration into the brain; however, within the tumor microenvironment, its expression appears to induce T-cell dysfunction." (PMID 38299146, 2023). "Upon capture of tumor antigens, antigen-presenting DCs produce CXCL16 that recruit CXCR6-expressing effector T cells in tumor tissue." (PMID 35757015, 2022).
tumor (continued). "Of note, compared with IL1R1− Treg cells or CD4+ T cells, IL1R1+ Treg cells expressed higher levels of CXCR6, which was recently reported to be critical for anti-tumour activity of cytotoxic T cells in a mouse model." (PMID 35545675, 2022). "We noted that the DEGs between the two T-cell clusters were consistent with the DEGs identified between ERG+ and ERG− tumor cells, with FOSB, FOS, and JUN overexpressed in ERG+ tumor cells while CXCR6 and DUSP4 were overexpressed in ERG- tumor cells." (PMID 35013146, 2022). "CXCL16, the chemokine ligand of CXCR6, was detected in supernatants from the majority of dissociated tumour and GNS cell samples." (PMID 35464424, 2022). "As CXCL16 is the ligand for CXCR6 which is expressed mostly on NKT cells, the cell frequencies of CXCR6+ NKT cell in tumor tissues of various groups were evaluated by flow cytometry." (PMID 34983554, 2022). "Several previous studies and reviews highlighted the up-regulation of CXCL16 and/or CXCR6 by tumor cells and their role in tumor growth, migration and invasiveness." (PMID 36311728, 2022). "We demonstrate a higher CXCR6 expression of NK cells in tumor of JORRP patients and enhanced CXCR6 expression on NK cells cocultured with HPV11-E6-E7-overexpressing SNU-1076 cell lines." (PMID 35350785, 2022). "Cxcr6-deficient mice showed reduced infiltration of tumors by activated CD8+ T cells and impaired tumor regression following treatment by local irradiation of the tumor." (PMID 36311728, 2022). "The expression of CXCR6 in human tumor tissues is closely related to the abundance of cytotoxic T lymphocyte (CTL), and it inhibits tumor growth by maintaining the survival of CTL, which is the most important among all chemokine receptors." (PMID 36230570, 2022). "In the Cancer Genome Atlas (TCGA) database, CXCR6 in tumor tissue correlated highly with CD8 expression and less with expression of CD4 and NK cells." (PMID 36311728, 2022). "Our findings demonstrated that the CXCL16 expression on LSECs induced by simvastatin attracted CXCR6+ NKT cells in the liver to inhibit tumor growth, which is consistent with previous studies." (PMID 34983554, 2022). "Breaking CXCR6-mediated retention in the tumor by anti-CXCL16 treatment resulted in more T cells egressing to the distant lung tissue and a decrease metastatic tumor burden." (PMID 36311728, 2022). "CXCR6-deficient CD8 T cells have weaker antitumor effects in murine melanoma, lung and colon cancer models and are less recruited at the tumor site even after anti-PD-1 treatment." (PMID 36429101, 2022). "A recently published study showed that CXCR6 is essential for sustained tumor control mediated by CD8+ cytotoxic T cells (CTLs) and improves TCF-1neg CTL antitumor activity in the TME." (PMID 36090326, 2022). "The levels of CXCL16 and CXCR6 are detected in various cancers and correlated with both better and worse survival, dependent on tumor types." (PMID 35959371, 2022). "But it was reported that CXCR6 upregulated in a portion of T cells 33, 34, and these CXCR6+ T cells would be recruited to the tumor tissue by the gradient of CXCL16." (PMID 34345211, 2021). "Among them, CXCR5 and CXCR6 have been found to play a role of tumor suppressor genes in the prognosis, which is controversial." (PMID 33829065, 2021). "To date, there has not been a review summarizing current knowledge on CXCL16 and its receptor CXC motif chemokine receptor 6 (CXCR6) in a tumor." (PMID 33800554, 2021). "Recently, CXCR6 was also reported to support migration of CD8 TRM cells to the lung after tumor vaccination." (PMID 34362825, 2021). "Functionally, releasing CXCR6 retention in the primary tumor amplifies tumor-derived TRMs in the lung and leads to superior protection against metastases." (PMID 33979626, 2021). "In particular, two genes, RUNX3 and CXCR6, have high positive correlation across six immune cell types and higher expressions in tumor samples than normal samples." (PMID 33919884, 2021).
tumor (continued). "CXCL16/CXCR6 signaling promotes the modulation of GAMs toward an anti-inflammatory/pro-tumor phenotype, and also restrains microglia polarization toward an inflammatory phenotype upon LPS and IFNγ stimulation." (PMID 34071306, 2021). "Our data showing an intrinsic requirement for CXCR6 expression on CD8 TRM cells led us to assess its role in mediating tumor protection." (PMID 34362825, 2021). "The mutual binding of CXCL16 and CXCR6 involves a variety of biological activities, including cell adhesion and anti-tumor immunity." (PMID 34676171, 2021). "In particular, sCXCL16 causes infiltration of the tumor by activated NK cells and CD8+CXCR6+ T cells." (PMID 33800554, 2021). "We found that in comparison to CXCR6− cells, the CXCR6+ TEff/EM cells remained in the tumor, validating the preference of the TEff/EM p4 population to stay in the tumor to become tumor TRMs." (PMID 33979626, 2021). "Analysis of endpoint tumors from mice that were treated with OT1+Mrb OVA showed that CXCR6 expression was seen predominantly in tumor-specific CD90.1+ OT1, but less frequently in CD90.1− CD8+ T cells." (PMID 34607898, 2021). "Luc+Pmel cells were isolated 7, 14, or 35 d after tumor excision and analyzed by flow cytometry for CXCR6 expression." (PMID 34362825, 2021). "We showed that transferred CXCR6+ tumor TEff/EMs were more likely to be trapped in the recipient tumor than their CXCR6− counterparts." (PMID 33979626, 2021). "CXCR6 functions as the receptor of CXCL16, and the CXCL16/CXCR6 signaling system is involved in the progression of tumor growth." (PMID 34722241, 2021). "Since CD2, CD3D, CD3E, and CXCR6 predict very favorable prognosis in CSCC, we evaluated the association of this new signature at transcriptomic level with the presence of tumor-infiltrating immune cell populations in CSCC." (PMID 34692491, 2021). "CXCL16 is the ligand of CXCL6, and CXCR6 upregulation is critical for continuous tumor control mediated by CD8+ cytotoxic T cells." (PMID 35127816, 2021). "This suggested that breaking CXCR6-mediated retention in the tumor resulted in more T cells egressing to the distant lung tissue." (PMID 33979626, 2021). "CXCR6 on tumor-specific T cells then engages with CXCL16 derived from the TME and facilitates T-cell retention." (PMID 34607898, 2021). "To approach the retention mechanism separating T cells that remain in the tumor versus those that leave to travel to remote tissues, we identified CXCR6 as a key player." (PMID 33979626, 2021). "We directly compared the levels of CXCR6+ on tumor TRMs versus TEff/EMs and found that overall, more TEff/EM cells expressed CXCR6+." (PMID 33979626, 2021). "It has been postulated that this effect is related to the increased expression of mCXCL16 in the plasma membrane and co-expression of CXCR6, which results in contact inhibition of tumor cell growth." (PMID 33800554, 2021). "When CXCR6 expression was compared between OT1 CD8+ T cells in tumor, spleen, and lymph node tissues of OT1+Mrb OVA-treated mice that had reached endpoint, only tumor-infiltrating OT1 T cells showed high CXCR6 expression." (PMID 34607898, 2021). "Then, we used flow cytometry to label and analyze the number of CCR3+, CCR9+, CCR10+, CXCR2+, CXCR5+, and CXCR6+ cells expressed different isotype antibodies including IgA, IgG, and IgM in the lung metastases of cKO and control tumor-bearing mice." (PMID 33707428, 2021). "As a chemokine, the binding of CXCL16 to its sole receptor CXCR6 can involve biological activities such as cell adhesion and anti-tumor immunity." (PMID 34676171, 2021). "The number of CXCR6-positive T cells were increased in the tumor tissues after treatment with iPS-ML-41BBL compared to that with control iPS-ML." (PMID 33669419, 2021). "We found that the PBNK cells express prime chemokine receptors, such as CXCR3, CXCR4, CCR5, and CXCR6, that match chemokines produced by the studied tumor cells." (PMID 33919155, 2021).